OR12D3 (olfactory receptor family 12 subfamily D member 3)
Description:
Odorant receptor.
Synonyms: hs6M1-27
Tractability: Antibody: UniProt places it where antibodies can reach, with medium confidence; UniProt predicts a signal peptide or a membrane-spanning region; its Gene Ontology location is reachable by antibodies, with medium confidence.
Gene: Protein-coding gene on chromosome 6 (29,373,423 to 29,375,291, reverse strand). Ensembl gene ENSG00000112462.
Subcellular location: Cell membrane
Pathways (Reactome):
Sensory Perception: Expression and translocation of olfactory receptors
Gene Ontology:
Molecular function: odorant binding; olfactory receptor activity; G protein-coupled receptor activity
Biological process: detection of chemical stimulus involved in sensory perception of smell; G protein-coupled receptor signaling pathway
Cellular component: membrane; plasma membrane
Genetic constraint (gnomAD): Loss-of-function variants: 1 observed, 1.63 expected, observed/expected ratio (o/e) 0.61, 90% interval 0.2 to 1.81. That is too few expected variants to judge how well the gene tolerates losing a copy. Missense variants: 332 observed, 404.45 expected, observed/expected ratio (o/e) 0.82, 90% interval 0.75 to 0.9. Synonymous variants: 141 observed, 144.36 expected, observed/expected ratio (o/e) 0.98, 90% interval 0.85 to 1.12.
Homologues: Orthologues: chimpanzee OR12D3 (99% identical), macaque OR12D3 (96% identical), pig OR12D3 (84% identical), rabbit OR12D3 (83% identical), rat Or12d17 (79% identical), mouse Or12d17 (79% identical). Paralogues in human: OR12D2 (65% identical), OR12D1 (50% identical), OR7A17 (43% identical), OR1A1 (42% identical), OR1E1 (42% identical), OR2A12 (42% identical), OR4D5 (42% identical), OR7D2 (42% identical), OR1A2 (42% identical), OR4E2 (42% identical), OR7A10 (42% identical), OR7D4 (42% identical), and 116 more.
Diseases named in the same sentence as OR12D3 in open-access papers:
OR12D3 is named in the same sentence as 3 diseases in open-access papers, as found by Europe PMC text mining. Sharing a sentence is not in itself a finding about the gene and the disease. The quoted sentences say what the papers report.
endometrial cancer (1 paper, 2019). Primary or metastatic malignant neoplasm involving the endometrium (mucous membrane that lines the endometrial cavity). "The OR12D3 gene has been associated with several carcinomas such as stomach cancer, endometrial cancer, and liver cancer." (PMID 31092860, 2019).
OR12D3 also shares sentences with these, for which no sentence is quoted: carcinoma (1 paper); stomach cancer (1).